FOSB (FosB proto-oncogene, AP-1 transcription factor subunit)
Diseases named in the same sentence as FOSB in open-access papers (continued):
Sharing a sentence is not in itself a finding about the gene and the disease.
tumor (continued). "ZFP36 is downregulated in the tumor compared with normal samples, and co‐expressed with JUN, JUNB, FOS, and FOSB, downregulation of which was associated with poor outcomes and BC progression." (PMID 35037412, 2022). "The measured data showed that FOSB decreased significantly after subcutaneously compared with the control group (n = 3), and the growth rate of the subcutaneous tumor was slower than that of the control group (*P < 0.05)." (PMID 36311014, 2022). "We noted that the DEGs between the two T-cell clusters were consistent with the DEGs identified between ERG+ and ERG− tumor cells, with FOSB, FOS, and JUN overexpressed in ERG+ tumor cells while CXCR6 and DUSP4 were overexpressed in ERG- tumor cells." (PMID 35013146, 2022). "Accordingly, FOSB inhibition blunted acquired resistance and extended survival of tumor-bearing mice treated with SCD inhibitor." (PMID 33568479, 2021). "Note that the effect of FOSB shRNA is partial, likely due to limited spread of lentivirus inside the tumor bed." (PMID 33568479, 2021). "Genes regulated by EHF_extended, BATF_extended, and CD59_extended were highly upregulated in advanced tumor cells, while genes regulated by ATF3, JUNB_extended, and FOSB_extended were upregulated in early tumor cells." (PMID 33783985, 2021). "Nude mice experiments confirmed that knock out of FOSB markedly increased MDA-MB-231 cells tumor growth." (PMID 32477007, 2020). "Many upregulated genes in the heat map have been reported to promote tumor metastasis, such as FOSB, OLR1, S100A9, MMP9, and ANGPTL4 36-40." (PMID 31598162, 2019). "Induction of FOSB was of particular interest, due to its known tumor suppressive effects and because the induction occurred in lung epithelial cancer cells but not in the control cell line, a normal human bronchial epithelial line, BEAS-2B." (PMID 30658436, 2019). "Combining whole-genome DNA and RNA sequences, we find rearrangement of FOS in five tumours and of FOSB in one tumour." (PMID 29858576, 2018). "The boxplots showed that the expression level of EGR1, FOS, and FOSB was significantly lower in primary tumor than that in the normal liver for LIHC patients from TCGA (p<0.001)." (PMID 30228980, 2018). "The FOSB gene is involved in cell proliferation, differentiation and transformation in several tumor types." (PMID 23181129, 2012). "Another potential target for miR-1247 is FosB, which dimerizes with Jun protein to activate transcription of proteases involved in tumor migration and invasion." (PMID 21698188, 2011). "While a very low or negligible expression of cJun, JunB, JunD, cFos, FosB, Fra-1 and Fra-2 was observed in normal adjacent tissues, the majority of them showed significantly elevated expressions in tumor tissues." (PMID 19758438, 2009). "Our own prior investigations have shown that FosB is highly expressed in more differentiated, hormone-receptor-positive tumours." (PMID 15928662, 2005). "High expression of FOSB+, NEAT1+, or XIST+ tumor cell-associated genes such as FSTL3, VTN, PAPPA, CCN1, RRAD, and GPRIN3 may predict poor survival in patients with LUSC, suggesting that these genes act as prognosis biomarkers." (PMID 37430270, 2023). "FOSB+ tumor cells were found mainly in the PD-1 and IgG groups." (PMID 37430270, 2023). "Upon Metascape analysis, FOSB+ tumor cells were found to show characteristics of extracellular matrix (ECM) organization, focal adhesion, and positive regulation of epithelial cell migration, based on the upregulated DEGs between the FOSB+ tumor cells and other malignant epithelia." (PMID 37430270, 2023). "FOSB (AP-1 transcription factor subunit) is a proto-oncogene in many tumor types." (PMID 36311014, 2022).
tumor (continued). "SETDB1 could also inhibit T cell cytotoxicity and promote tumor growth and immune cell infiltration via the FOSB/miR-22/BATF3/PD-L1 axis." (PMID 35497876, 2022). "Furthermore, SETDB1 silencing promoted the T cell-mediated cytotoxicity to tumor cells via the FOSB/miR-22/BATF3/PD-L1 axis and hindered CRC tumor growth in mice while leading to decreased immune cell infiltration." (PMID 35497876, 2022). "Additionally, the protein expression of SETDB1, BATF3, and PD-L1 was diminished while FOSB expression was upregulated in the presence of sh-SETDB1+OE-NC while opposite results were detected in the tumor tissues of mice treated with sh-SETDB1+OE-BATF3." (PMID 35497876, 2022). "Moreover, TGF-β1 can activate PI3K/AKT/mTOR signaling or promote expression of EGFR and FosB to facilitate cancer cell motility, invasion and tumor metastasis." (PMID 34203341, 2021). "However, in SCD inhibitor–treated mice, where late-stage tumors overexpress SCD, and presumably acquire resistance in vivo through FOSB overdrive, FOSB shRNA slowed tumor growth and improved survival of mice." (PMID 33568479, 2021). "Next, to test whether reducing FOSB levels in advanced SCD inhibitor–treated tumors (when they presumably start acquiring resistance to the inhibitor) exerted any effect on tumor growth and survival, we performed an additional experiment." (PMID 33568479, 2021). "FOSB functions downstream of Ras/MAPK signaling as a tumor promoter most of the time." (PMID 34345013, 2021). "These invasive properties of FOSB mutant tumor cells are characteristic of PHE in patients." (PMID 33377124, 2020). "The effect of FOSB on TNBC tumor growth in vivo was investigated in a mice tumor xenograft model." (PMID 32477007, 2020). "The tumor cells also show diffuse nuclear immunoreactivity for FOSB." (PMID 32316685, 2020). "In addition, FOSB overexpression triggers cancer cell death, suggesting a tumor-suppressive role of the protein." (PMID 30658436, 2019). "Interestingly, they include EGR1, ETV4, ETV5 and FosB that have been associated with EMT and tumour aggressiveness in several cancers." (PMID 28651004, 2017). "We could precisely estimate FOSB expression in tumor cells because the intensity of FOSB expression in background cells was stronger than that in tumor cells in EHE, AS, KS and ES cases which showed limited, weak or no reactivity of FOSB." (PMID 27515856, 2016). "We should check HE stained sections corresponding to IHC specimens to confirm whether FOSB-positive cells are tumor cells." (PMID 27515856, 2016). "To address whether FOSB expression is associated with TNBC progression, we analyzed FOSB expression in various grades of tumor samples from TNBC patients by immunohistochemical analysis." (PMID 27248170, 2016). "FOSB expression was often observed in various background cells which often intermingled with tumor cells; therefore, such positivity in background cells may have misled us into placing a higher valuation of FOSB expression." (PMID 27515856, 2016). "Therefore, we had some difficulty in estimating the true FOSB positivity in tumor cells except for PHE." (PMID 27515856, 2016). "Strikingly, treatment with metformin might reduce tumor growth, mainly by inducing the expression of a set of genes FOSB, EGR1, ZFP36, GPR183, ATF3, and NR4A1 which are involved in DNA-binding transcriptional activation, response to hormones and the Dcp1-Dcp2 mRNA-decapping complex." (PMID 39026155, 2024).
tumor (continued). "Moreover, chemotherapeutic agent-induced FOSB expression might contribute to a counterproductively poor prognosis in NSCLC by endowing tumor cells with increased proliferation and invasiveness." (PMID 39164746, 2024). "Thus, the present study further demonstrated that silencing of STEDB1 could dramatically downregulate the expression of PD-L1, thereby promoting T cell cytotoxicity to tumor cells via the FOSB/miR-22/BATF3 axis." (PMID 35497876, 2022). "Finally, in vivo experimental results revealed that SETDB1 silencing could impede CRC tumor growth in mice and immune cell infiltration via the FOSB/miR-22/BATF3/PD-L1 axis." (PMID 35497876, 2022). "Moreover, the translocation results in the overexpression of FOSB protein in patient tumor samples." (PMID 33377124, 2020). "In addition, FOSB expression was also detected within the tumor (right)." (PMID 27248170, 2016). "For a deeper understanding of the oncogenic mechanisms of the C0 MAFF+ tumor cell subtype, we analyzed the TFs within this subtype and identified the top five active TFs: KLF6, ATF3, JUN, FOS, and FOSB." (PMID 40936936, 2025). "However, the underlying interacting proteins of FOSB in NSCLC have rarely been characterized to date, despite the fact that they may have overwhelming impacts on FOSB-mediated transcriptional events that determine the fate of tumor cells." (PMID 39164746, 2024). "When FOSB expression is suppressed by this epigenetic alteration, TNBC cells demonstrate accelerated tumor growth both in vitro and in vivo." (PMID 39120328, 2024). "FOSB and NKX2‐1 showed significant upregulation in the CTumour group compared with the Tumour group." (PMID 39113235, 2024). "Therefore, FOSB+ tumor cells may possess invasive and migrative properties." (PMID 37430270, 2023). "We found that FOSB and RUNX1, as important drivers of tumour proliferation and invasion, were significantly associated with the OS of EOC patients and upregulated during EMT." (PMID 37817210, 2023). "Sodium selenite treatment upregulated pro-apoptotic, apoptotic, and tumor suppressor genes such as ATF3, FOSB, GADD45B, DUSP8 and ACHE, and downregulated tumor cell survival genes such as SCD, LRP1, RAB31, SRPX2, PDK1 and CSGALNACT1." (PMID 36059619, 2022). "Western blot was conducted to evaluate the expression of angiopoietin-2 (ANGPT2), FosB, MS4A4A, and Versican (VCAN) in tumor tissue and normal tissue." (PMID 36569220, 2022). "NK_c3 and NK_c5 were mainly derived from non-tumor liver tissues (23.57% and 5.97%, respectively) and characterized by high expression of transcription factors such as FOS, FOSB, FOXP1, and ATF4, and two genes involved in the NF-κB pathway, NFKBIA and NFKBIZ." (PMID 33298893, 2020). "In this study, we identified FOSB as a novel EZH2 downstream target gene in TNBC, and inhibition of which resulted in tumor growth and EZH2is resistance." (PMID 32477007, 2020). "The tumor expresses a fusion gene between FOSB and either SERPINE1, ACTB, or WWTR1, which results in an overexpression of FOSB." (PMID 33194900, 2020). "This is intriguing as in human tumours FOS and FOSB rearrangements have so far only been identified in vascular and bone forming tumours lacking malignant potential." (PMID 31741049, 2020).
tumor (continued). "In these 55 samples, we found FOSB and FOS breakapart signals in 1 and 48 tumours, respectively (89% in total)." (PMID 29858576, 2018). "The most highly upregulated genes (e.g. CYR61, DUSP1, FOSB and FOS), which increased in almost all tumours, were early-response genes." (PMID 29214214, 2017). "In TNBC, FRA1 controls tumor cell growth and metastasis through repression of CDH1 in poorly differentiated cells which lack FOSB expression." (PMID 27248170, 2016). "On IHC, diffuse and strong expression of FOSB was observed in all PHE cases, while the other tumor types including 3 EHE, 6 AS, 4 KS and 3 ES cases demonstrated limited (10 %) and weak FOSB expression." (PMID 27515856, 2016). "By binding to JUN (also JUNB or JUND) or FOS, FOS (also FOSB, FRA1 or FRA2) forms a well-known heterodimeric or homodimeric transcription factor AP-1 which could be oncogenic or tumor-suppressive depending on the cell type." (PMID 38410462, 2024). "The UMAP plots showed that the LHB, GNRHR, TGFBR3L, FOSB and SCGN genes were highly expressed mainly in the epithelial cells of the normal group, while their expression was low in the epithelial cells of the tumour group." (PMID 39548559, 2024). "When comparing the primary tumor and the cranial recurrence, 21 genes were significantly differentially expressed (|FC|≥2, FDR<0.05), with expression of the proto-oncogene FOSB increased over 100-fold in the cranial recurrence compared to the primary tumor." (PMID 36937401, 2023). "Tumor cells with fused genes showed overexpression of FOSB, FOS, and JUN, while tumor cells without fused genes overexpressed CXCR6 and DUSP4." (PMID 37736898, 2023). "Another, according to the Context++ score percentile (score > 70) in the TargetScanHuman, we selected the tumor suppressor USP49 with high Context++ score for the subsequent analysis when compared with IL17RD (score = 58), FOSB (score = 88) and SHROOM4 (score = 21)." (PMID 34075026, 2021). "Despite technical challenges, we injected FOSB shRNA or nontarget shRNA into the tumor through the same burr hole that was used to inject parental G82 GBM cells 10 days after tumor cell implantation." (PMID 33568479, 2021). "FOSB shRNA alone did not decelerate tumor growth or improve survival, confirming that FOSB has no significant role in tumor growth of parental cells." (PMID 33568479, 2021). "In those studies, normal and/or tumor tissues that underwent warm ischemia due to delayed processing after surgical incision demonstrated increased expression of FOS, FOSB, JUN, EGR1 as well as upregulation in immune system pathways compared to tissues processes immediately." (PMID 34814833, 2021). "To test whether protein expression correlates with mortality, we quantified the levels of FOSB and PCDHB13 in each tumor sample and normalized the values to the average from nine matched NAT samples." (PMID 30658436, 2019). "However, both c-FOS and FOSB were shown to be downregulated in NSCLC, suggesting a tumor suppressive role." (PMID 30658436, 2019). "The relative expressions of EGR1, FOS, and FOSB mRNA were 0.493±0.558-, 0.494±0.476-, and 0.500±0.551-fold downregulated in 20 tumor tissues versus adjacent nontumor tissues, respectively." (PMID 30228980, 2018). "In two out of the three PDXs, FosB was markedly elevated in NAT compared with both the tumor and non-tumor mammary gland from naive mice." (PMID 29057876, 2017). "There was a notable difference of FOSB positivity between PHE and other tumor types." (PMID 27515856, 2016). "IHC revealed diffuse and strong FOSB expression in all PHE cases, while the other tumor types demonstrated limited, weak or no FOSB expression." (PMID 27515856, 2016). "The three genes that were significant for ‘Time’, ‘T2’ and the ‘T3’ contrasts in the Tumor samples (JUN, FOSB and ABL1) were selected for technical validation with Real Time PCR (RT-PCR) analysis in the same Tumor tissues belonging to the 14 different patients analyzed by microarrays." (PMID 23308215, 2013).
tumor (continued). "FosB was detected as 1 or 2 bands at 48–55 kDa, with high expression in Ovcar5 and MCF7 cells, low protein expression in Ovcar8 cells and strong variations in the tumour samples." (PMID 18854825, 2008). "Moreover, endothelial cells of the tumor frequently show nuclear FOS and/or FOSB immunostaining pattern, and a subset of cases have a FOS or FOSB gene rearrangement detectable by florescence in-situ hybridization (FISH), findings suggestive of a neoplastic process." (PMID 39998691, 2025). "However, its copy number profile presented an abundance of CNV (49%) hardly compatible with a benign tumor and no FOS/FOSB gene fusions were detected by RNA sequencing." (PMID 35347251, 2022).